SCAMP3 (secretory carrier membrane protein 3)
Description:
Functions in post-Golgi recycling pathways. Acts as a recycling carrier to the cell surface.
Synonyms: C1orf3
Tractability: Antibody: UniProt predicts a signal peptide or a membrane-spanning region. PROTAC: UniProt records ubiquitination sites on it; ubiquitination databases record sites on it; its protein half-life has been measured.
Gene: Protein-coding gene on chromosome 1 (155,255,979 to 155,262,433, reverse strand). Ensembl gene ENSG00000116521.
Subcellular location: Membrane
Subcellular location (Human Protein Atlas): Vesicles
Gene Ontology:
Molecular function: ubiquitin protein ligase binding
Biological process: exocytosis; post-Golgi vesicle-mediated transport; protein transport
Cellular component: extracellular exosome; recycling endosome membrane; trans-Golgi network membrane; Golgi membrane; membrane
Genetic constraint (gnomAD): Loss-of-function variants: 30 observed, 46.08 expected, observed/expected ratio (o/e) 0.65, 90% interval 0.49 to 0.88. The upper end of that interval is the gene's LOEUF score, 0.88, which puts it in group 3 of 6, group 1 being the genes least tolerant of losing a copy. Missense variants: 394 observed, 445.89 expected, observed/expected ratio (o/e) 0.88, 90% interval 0.81 to 0.96. Synonymous variants: 168 observed, 175.05 expected, observed/expected ratio (o/e) 0.96, 90% interval 0.85 to 1.09.
Homologues: Orthologues: chimpanzee SCAMP3 (100% identical), macaque SCAMP3 (99% identical), dog SCAMP3 (97% identical), rabbit SCAMP3 (95% identical), pig SCAMP3 (94% identical), guinea pig SCAMP3 (93% identical), rat Scamp3 (91% identical), mouse Scamp3 (91% identical), tropical clawed frog scamp3 (61% identical), zebrafish scamp3 (61% identical), Drosophila melanogaster Scamp (41% identical), Caenorhabditis elegans scm-1 (38% identical). Paralogues in human: SCAMP1 (53% identical), SCAMP2 (49% identical), SCAMP4 (30% identical), SCAMP5 (29% identical).
Diseases named in the same sentence as SCAMP3 in open-access papers:
SCAMP3 is named in the same sentence as 24 diseases in open-access papers, as found by Europe PMC text mining. Sharing a sentence is not in itself a finding about the gene and the disease. The quoted sentences say what the papers report.
hepatocellular carcinoma (8 papers, 2017 to 2024). A malignant tumor that arises from hepatocytes. "Endocytosis-associated protein SCAMP3 was highly expressed and associated with poorer survival and progression in hepatocellular carcinoma (HCC)." (PMID 38460058, 2024). "In hepatocellular carcinoma cells, SCAMP3 knockdown has been shown to suppress cell proliferation, while HEATR6 has never been associated with tumorigenesis." (PMID 35453681, 2022). "In recent studies, researchers have reported SCAMP3 as a promoter of cell proliferation in hepatocellular carcinoma, glioma, and melanoma." (PMID 35681787, 2022). "While SCAMP3, which is overexpression in the hepatocellular carcinoma, has been found that its modification with ubiquitin and its interaction with ESCRT coordinate the regulation of endosome pathway and affect the efficiency of receptor down-regulation." (PMID 34112093, 2021). "Overexpression of SCAMP3 was found to be closely related to poor overall survival in human hepatocellular carcinoma and that knockdown of SCAMP3 decreased cell proliferation and cell cycle progression of HCC cells." (PMID 34426610, 2021). "Previous microarray data showed that SCAMP3 mRNA is highly expressed in hepatocellular carcinoma (HCC)." (PMID 29312605, 2017).
melanoma (6 papers, 2019 to 2023). A malignant, usually aggressive tumor composed of atypical, neoplastic melanocytes. "Other groups have published an accumulation of SCAMP3 melanoma knockout cells in the S and G2/M cell cycle phases and arrest in G1 in HCC SCAMP3 depleted cells." (PMID 35681787, 2022). "EFEMP1 and SCAMP3 knockdown significantly suppressed melanoma cell growth, but only EFEMP1 knockdown inhibited its motility abilities." (PMID 30754729, 2019). "After transfection of si-EFEMP1 and si-SCAMP3 into melanoma cells, the expression levels of individual genes were confirmed through Western blotting and real-time PCR." (PMID 30754729, 2019). "In conclusion, the results suggested that metformin treatment suppressed the motility and growth of melanoma cells due to direct modulation of miR-192-5p-EFEMP1 and miR-584-3p-SCAMP3 axes in melanoma cells." (PMID 31534778, 2019). "Furthermore, metformin also decreases cell growth and invasion of melanoma through modulation of miR-192-5p/EFEMP1 and miR-584 3p/SCAMP3 axes in a wide range of melanoma cell lines." (PMID 37370809, 2023). "Furthermore, miR-584 expression significantly inhibited melanoma cell growth through targeting SCAMP3." (PMID 30754729, 2019). "They used siRNA to investigate the effects of EFEMP1 and SCAMP3 knockdown on melanoma cell growth." (PMID 31534778, 2019). "The growth of melanoma tumors is inhibited following EFEMP1 and SCAMP3 silencing by miR-192-5p and miR-584-3p targeting, respectively." (PMID 33493138, 2021). "The AMPK activator Metformin also displays anti-cancer activity, particularly in cases of melanoma in which cancer cell growth is inhibited through direct effects on miR-192-5p-EFEMP1 and miR-584-3p-SCAMP3 pathways." (PMID 33493138, 2021). "We demonstrated that miR-192-5p and miR-584-3p played crucial roles in the regulation of melanoma cell growth or invasion ability through the targeting of EFEMP1 and SCAMP3, respectively." (PMID 30754729, 2019). "SCAMP3 has been identified to promote the proliferation of glioma and melanoma; however, no evident correlation has been found between SCAMP3 and its regulation of cell migration and invasion." (PMID 35681787, 2022). "The results indicated that metformin treatment suppressed the motility and growth of melanoma cells because it might directly modulate miR-192-5p-EFEMP1 and miR-584-3p-SCAMP3 axes in melanoma cells." (PMID 30754729, 2019). "Our findings indicated that miR-192-5p and miR-584-3p might contribute to metformin-induced growth and motility suppression in melanoma cells through silencing their target genes EFEMP1 and SCAMP3." (PMID 30754729, 2019). "In conclusion, our study demonstrated that metformin treatment suppressed melanoma cell growth and invasion ability, which might be accomplished partially through the modulation of both miR-192-5p/EFEMP1 and miR-584-3p/SCAMP3 axes." (PMID 30754729, 2019).
breast carcinoma (3 papers, 2020 to 2025). "Since SCAMP3 is overexpressed in several cancers, we evaluated its expression in breast cancer patients included in the TCGA database using the UALCAN and Human Protein Atlas portals." (PMID 35681787, 2022). "Given that inhibition of SCAMP3 efficiently promotes cell death, decreases cell migration, and invasion, it indicates the potential to tailor specific therapies to breast cancer patients." (PMID 35681787, 2022). "Given that our results suggested that SCAMP3 knockout would decrease tumor growth, we developed breast cancer xenograft models using WT and SCAMP3 knockout cells." (PMID 35681787, 2022). "It is important to note that SCAMP3 is highly expressed in breast cancer and patients showed reduced survival." (PMID 35681787, 2022). "The potential role of SCAMP3 down-regulation needs to be further explored in breast cancer patients with resistance to TKI." (PMID 35681787, 2022). "We also evaluated the expression of SCAMP3 in breast cancer subclasses." (PMID 35681787, 2022). "The potential role of SCAMP3 in breast cancer remains unexplored." (PMID 35681787, 2022). "Additionally, analysis of TCGA data revealed elevated SCAMP3 expression in breast cancer tumors." (PMID 35681787, 2022). "Through our findings, we demonstrate, for the first time, the role of SCAMP3 in promoting breast cancer proliferation, migration, and invasion, through negative regulation of EGFR degradation, as well as AKT, ERK, and STAT signaling pathways." (PMID 35681787, 2022). "Our findings indicate that SCAMP3 could contribute to TNBC development through the regulation of multiple pathways and has the potential to be a target for breast cancer therapy." (PMID 35681787, 2022).
glioma (3 papers, 2021 to 2022). A benign or malignant brain and spinal cord tumor that arises from glial cells (astrocytes, oligodendrocytes, ependymal cells). "For instance, LGALS3, L1CAM, and SCAMP3 were associated with the shorten OS of glioma patients by promoting the proliferation or other malignant tumor characteristics of glioma." (PMID 33750478, 2021). "SCAMP3 is highly expressed in breast cancer, HCC and glioma." (PMID 35805075, 2022). "SCAMP3 looks like a pro-oncogenic protein whose increased expression significantly correlates with vascular invasion and tumor stage in HCC and with tumor size and poor overall survival in glioma." (PMID 35805075, 2022).
inflammatory breast carcinoma (2 papers, 2020 to 2022). An advanced, invasive breast adenocarcinoma characterized by the presence of distinct changes in the overlying skin. "Previously, we published SCAMP3 expression on TNBC inflammatory breast cancer (IBC) cells, IBC patient tumor tissues, invasive embolus structure, and lymphatic vessels." (PMID 35681787, 2022).
Obesity (2 papers, 2019 to 2024). Accumulation of substantial excess body fat. "The PPARG/SCAMP3 axis could be important for maintaining a balance between hypertrophic and hyperplastic expansion of adipose tissue in obesity." (PMID 31554889, 2019).
breast tumors (1 paper, 2022). "The analysis showed SCAMP3 overexpression in primary breast tumors (n = 1097) compared to normal tissues (n = 114)." (PMID 35681787, 2022).
invasive ductal carcinomas (1 paper, 2022). "We previously reported high SCAMP3 expression in invasive ductal carcinoma and inflammatory breast cancer tumors." (PMID 35681787, 2022). "Moreover, we identified the expression of the SCAMP3 protein in invasive ductal carcinomas." (PMID 35681787, 2022). "Previously, we published a novel study demonstrating an increased expression of SCAMP3 in inflammatory breast cancer (IBC) and invasive ductal carcinoma (IDC) tumor tissues." (PMID 35681787, 2022). "We confirmed the expression of SCAMP3 in invasive ductal carcinoma patient samples; however, we did not observe its expression in non-cancerous breast tissues." (PMID 35681787, 2022).
liver cancer (1 paper, 2023). An epithelial or non-epithelial malignant neoplasm that arises from the liver. "However, decreased expression of SCAMP3, a regulatory gene in the hypothalamus (3-vs.-5), can inhibit the occurrence of breast and liver cancer, promoting individual health." (PMID 36978553, 2023).
lung carcinoma (1 paper, 2021). "However, SCAMP3 was also reported to function as a novel tumor suppressor in lung cancer by modulating EGFR signaling and cytokinesis." (PMID 34426610, 2021).
pancreatic cancer (1 paper, 2021). "Inversely, proteins such as SCAMP3, whose mRNA transcript abundance was found to be increased in normal tissues relative to RCC tissues, and STUB1, which is considered a tumor suppressor in pancreatic cancer, were enriched in HK2 EVs relative to RCC EVs." (PMID 34331598, 2021).
Salmonella Infections (1 paper, 2009). Infections with bacteria of the genus SALMONELLA. "After Salmonella infection, SISTs (SCAMP3 tubules with no detectable LAMP1-HcRed), SIFs containing EGFP-SCAMP3 and SIFs with little EGFP-SCAMP3 were observed within the same cell." (PMID 19438519, 2009).
type 2 diabetes (1 paper, 2017). "Moreover, SCAMP3 is regarded as a positional and functional candidate gene for type 2 diabetes (T2DM)." (PMID 29312605, 2017).
virus infection (1 paper, 2021). "We demonstrated by immunoprecipitation assay that SCAMP3 associates with 3A protein and it colocalizes with 3A protein during virus infection." (PMID 34378951, 2021). "Here, we demonstrate by immunoprecipitation assay that SCAMP3 associates with 3A protein and colocalizes with 3A protein during virus infection." (PMID 34378951, 2021).
tumor (9 papers, 2017 to 2025). "Consistent with the findings that identified SCAMP3 as a tumor-promoting protein, our results indicated that SCAMP3 plays a significant role in the oncogenesis and progression of TNBC through the regulation of EGFR degradation and other multiple pathways." (PMID 35681787, 2022). "For the first time, these findings demonstrate the tumor-promoting role of SCAMP3 in TNBC and its association with EGFR and other receptor tyrosine kinases and expose the potential to develop SCAMP3-targeted anticancer therapies to increase patient survival." (PMID 35681787, 2022). "This study provides evidence for SCAMP3′s TNBC tumor-promoting role and its potential as a target therapy for this disease." (PMID 35681787, 2022). "We published an increase in SCAMP3 expression in the hallmark emboli structure and in lymphatic vessels of IBC tumor samples." (PMID 35681787, 2022). "TNBC xenograft models showed that SCAMP3 depletion delayed tumor cell proliferation at the beginning of tumor development and modulated the expression of genes from the PDGF pathway." (PMID 35681787, 2022). "SCAMP3 level was positively correlated with disease stages and tumor grades and negatively correlated with patient survival; SOX4, STK39, TARBP1, and TDRKH can be regarded as potential prognosticators and therapeutic targets for HCC." (PMID 34277395, 2021). "SCAMP3 expression was significantly correlated with vascular invasion, tumor stage and poor survival." (PMID 29312605, 2017). "The results showed that SCAMP3 expression was significantly correlated with vascular invasion (P = 0.004) and tumor stage (P = 0.001)." (PMID 29312605, 2017). "The previous study, in which cDNA microarrays were used to characterize patterns of gene expression in HCC, demonstrated that SCAMP3 was highly expressed in HCC tissue compared to those seen in non-tumor liver tissues." (PMID 29312605, 2017). "The increased SCAMP3 expression was significantly correlated with vascular invasion (P = 0.004) and tumor stage (P = 0.001)." (PMID 29312605, 2017). "In conclusion, our study showed that the expression of SCAMP3 was up-regulated in human HCC tissue, and the up-regulated SCAMP3 was closely related to vascular invasion, tumor stage and indicated poor survival of HCC." (PMID 29312605, 2017). "Contrary to our hypothesis, SCAMP3 depletion only reduced tumor volume in the first week of the study." (PMID 35681787, 2022). "Recently, studies have emerged to show the tumor-related role of SCAMP3 in a variety of cancers." (PMID 35681787, 2022). "We investigated the role of SCAMP3 in the regulation of TNBC tumor growth." (PMID 35681787, 2022). "Furthermore, the Cox’s proportional hazards Regression model showed that the expression of SCAMP3 (P = 0.001), tumor size (P = 0.011) and vascular invasion (P = 0.000) were independent prognostic factors of overall survival." (PMID 29312605, 2017). "Furthermore, studies should be carried out to investigate whether the tumor microenvironment negatively influences the capacity of SCAMP3 depleted cancer cells to alter tumor progression." (PMID 35681787, 2022). "We hypothesized that SCAMP3 depletion would affect tumor development and progression." (PMID 35681787, 2022). "Elsewhere, the secretory-carrier-membrane-protein 3 (SCAMP3) was shown to promote TNBC stemness and progression (cell proliferation, clonogenicity, tumour spheroid formation and migration in vitro and tumour growth in vivo) through c-Myc." (PMID 39531198, 2025). "When all tumor samples were evaluated together the correlation of GZMH, ABL1, IL-7, LY9, IL-12, SCAMP3, and CD244 were highly significant (p < 1 × 10−6)." (PMID 29587383, 2018). "First, the lack of SCAMP3 delays the proliferation of tumor-initiating cells that affects the initial stage of tumor development." (PMID 35681787, 2022). "This study investigated the role of SCAMP3 in promoting TNBC cell response and tumor progression." (PMID 35681787, 2022).
tumor (continued). "Contrary to what we expected, SCAMP3 depletion did not decrease tumor volume." (PMID 35681787, 2022). "Second, SCAMP3 depletion does not affect primary tumor growth, but it might regulate metastasis." (PMID 35681787, 2022).
cancer (6 papers, 2019 to 2022). A tumor composed of atypical neoplastic, often pleomorphic cells that invade other tissues. "Some studies have demonstrated that activation of wild-type or mutated EGFR cancer cells stimulates SCAMP3 phosphorylation, promoting the interaction of both proteins." (PMID 35681787, 2022). "Although SCAMP3 has been associated with cancer cell proliferation, only one study correlated this protein with invasion." (PMID 35681787, 2022). "Therefore, it is necessary to explore the role of SCAMP3 in this type of cancer and how it is associated with IBC metastasis." (PMID 35681787, 2022). "Based on our previous findings and the limited number of studies that evaluate the role of SCAMP3 in cancer, we sought to investigate the role of SCAMP3 in TNBC and the molecular mechanism behind its function." (PMID 35681787, 2022). "Chmp1A, an ESCRT protein, inhibits cancer cell proliferation, invasion and signaling activity via MVB formation, highlighting the potential role of SCAMP3 during cancer development." (PMID 33493138, 2021). "For example, SCAMP3 protein was found to be an important regulator of EGFR trafficking and was suggested to play a critical role in EGFR-driven cancers." (PMID 33946771, 2021). "Our results contrast with recent reports from other groups in other cancer types, which show that SCAMP3 depletion did not affect cancer cell motility." (PMID 35681787, 2022).
infection (2 papers, 2009 to 2021). The state of being infected such as from the introduction of a foreign agent such as serum, vaccine, antigenic substance or organism. "However, infection with wt S. Typhimurium caused the frequent appearance of distinct structures marked by SCAMP3 that often extended to the periphery of the cell." (PMID 19438519, 2009). "The localization of SCAMP3, 3A-FLAG, and PI4KIIIβ in RD cells at 6 h of EV-A71 infection was studied using pEGFP-C3-SCAMP3, anti-FLAG (red color), and anti-PI4KIIIβ (white color) antibodies in an immunofluorescence assay by confocal microscopy." (PMID 34378951, 2021). "Upon infection of cells with a SCAMP3 knockout construct, PI4KIIIβ and phosphatidylinositol-4-phosphate (PI4P) colocalization with EV-A71 3A protein decreases; viral RNA synthesis also decreases." (PMID 34378951, 2021). "The localization of 3A-FLAG and SCAMP3 in RD cells, following a time course of EV-A71 infection, was studied using anti-FLAG (red color) and anti-SCAMP3 (green color) antibodies in an immunofluorescence assay (IFA) by confocal microscopy." (PMID 34378951, 2021). "The results showed that viral 3A/3AB were exclusively within the membrane fraction; viral 3Dpol, SCAMP3, PI4KIIIβ, and ACBD3 were present in both fractions to various degrees during EV-A71 infection." (PMID 34378951, 2021). "After infection with wt S. Typhimurium for 14 h, we found that TPR overexpression inhibited, but did not abolish, the appearance of SCAMP3 tubules." (PMID 19438519, 2009).
SCAMP3 also shares sentences with these, for which no sentence is quoted: glioblastoma multiforme (1 paper); invasive breast carcinoma (1); liver cirrhosis (1); liver fibrosis (1); lung adenocarcinoma (1); myocarditis (1); ovarian carcinoma (1).